CRP (C-reactive protein)
Diseases named in the same sentence as CRP in open-access papers (continued):
Sharing a sentence is not in itself a finding about the gene and the disease.
retinopathy of prematurity (1 paper, 2016). A bilateral retinopathy characterized by neovascularization, scarring, retinal detachment, and eventually blindness. "Furthermore infants fed with lutein-supplemented formula seem to develop less severe retinopathy of prematurity (ROP) than control group and they have lower value of plasma C-reactive protein (CRP)." (PMID 27656124, 2016).
retroperitoneal sarcoma (1 paper, 2022). A sarcoma involving a retroperitoneal space. "The prognosis of retroperitoneal sarcoma can be determined by serum markers of the innate inflammatory response [e.g., neutrophil-to-lymphocyte ratio (NLR) and C-reactive protein (CRP)]." (PMID 36313634, 2022).
rhinosporidiosis (1 paper, 2023). Chronic, localized granulomatous infection of mucocutaneous tissues, especially the nose, and characterized by hyperplasia and the development of polyps. "Changes in inflammatory markers and acute phase reactants- ESR, CRP, and Ferritin in rhinosporidiosis were evaluated in our study." (PMID 38090617, 2023).
salmonellosis (1 paper, 2021). Infections with bacteria of the genus salmonella. "Salmonellosis can cause the increase in C-reactive protein values (CRP), erythrocyte sedimentation rate (ESR) and body temperature." (PMID 34943308, 2021).
senility (1 paper, 2024). "In the present study, senility, anti-Ro52 antibodies, and high CRP and CEA levels were found to be associated with the development of RPILD, which is compatible with previous research." (PMID 38337419, 2024).
Sézary syndrome (1 paper, 2024). "In a study investigating the prognostic significance of CRP levels in patients with MF and Sézary syndrome, it was demonstrated that elevated CRP levels were associated with advanced stages and lower treatment response rates." (PMID 38332520, 2024).
sick sinus syndrome (1 paper, 2020). A constellation of signs and symptoms which may include syncope, fatigue, dizziness, and alternating periods of bradycardia and atrial tachycardia, which is caused by sinoatrial node dysfunction. "In the univariate Cox regression analysis, sick sinus syndrome (p = 0.005), prior AF (p < 0.001), mitral A velocity (p = 0.008), and hs-CRP (p = 0.013) showed significant association with the increased risk of AHREs." (PMID 33207668, 2020).
small artery occlusion (1 paper, 2016). "The objective of our study was to investigative the association between hs-CRP levels and outcomes of patients with small-artery occlusion (SAO)." (PMID 27555819, 2016).
small bowel cancer (1 paper, 2025). "The gold standards in recent decades were C-reactive protein (CRP) and faecal calprotectin (FC), but their specificity for small bowel cancer was low." (PMID 41008635, 2025).
small bowel Crohn disease (1 paper, 2017). A Crohn disease involving a pathogenic inflammatory response in the small intestine. "Correlations between the Lewis score and Harvey–Bradshaw Simple Index, C-reactive protein, and small bowel transit time in adult patients with small bowel Crohn's disease." (PMID 28816962, 2017).
spasm (1 paper, 2026). "Lower high-density lipoprotein cholesterol (HDL-C) was associated with coronary spasm in both clusters, while higher hs-CRP was independently associated with spasm only in the inflammation-dominant cluster." (PMID 41906614, 2026).
spinal cord diseases (1 paper, 2016). "Levels of CRP in the urine of dogs with spinal cord disorders with micturition problems were elevated." (PMID 26746899, 2016). "Evaluating detectable urine samples only a significant higher concentration of CRP/Crea-levels could be found comparing the control group and different neurological disorders and the control group with spinal cord disorders with micturition problems." (PMID 26746899, 2016). "Therefore, we hypothesize that CRP and NGF are measurable in serum and urine samples and can be used as biomarkers in either serum or urine to distinguish between micturition disorders caused by neurologic dysfunctions or bacterial cystitis in dogs with spinal cord disease." (PMID 26746899, 2016). "The CRP levels in serum were significantly different in the control group and the spinal cord disorders without micturition problems (p = 0.0181), no further significant differences could be evaluated." (PMID 26746899, 2016). "The purpose of this study was to prove the hypothesis that C-reactive protein (CRP) and nerve growth factor (NGF) may be potential biomarkers for lower urinary tract disorders and may be able to distinguish between micturition dysfunctions of different origin in dogs with spinal cord diseases." (PMID 26746899, 2016). "In 9/15 dogs with spinal cord disorders without micturition problems CRP was measurable with a mean concentration of 14,764 ng/ml (range: 0–92,035 ng/ml) and in 12/27 dogs with micturition problems a mean concentration of 9235 ng/ml (range 0–81,719 ng/ml) could be detected." (PMID 26746899, 2016). "From these data we conclude that neither CRP nor NGF in urine or serum can be considered as reliable biomarkers for micturition disorders in dogs with spinal cord disorders in a clinical setting, but their production might be part of the pathogenesis of such disorders." (PMID 26746899, 2016). "In the first group including all dogs, significant differences measuring the CRP/Crea-ratio could be found between the spinal cord disorders without micturition problems and the control group (p = 0.0118) as well as with different neurological disorders (p = 0.0445)." (PMID 26746899, 2016).
spinal meningioma (1 paper, 2022). Spinal meningioma isa rare type of spinal cord cancer. "However, multivariable analysis showed that serum CRP and plasma fibrinogen are not independently associated with the MIB-1 labeling index in a cohort also investigating spinal meningiomas." (PMID 35205781, 2022).
spindle cell carcinoma (1 paper, 2023). "Good prognostic factors include surgical resectability, limited disease extent, good performance status, right lung location, and central site, combination with adenocarcinoma or spindle cell carcinoma, and normal C-reactive protein levels." (PMID 36769639, 2023).
spirochetal infections (1 paper, 2018). "Moreover, increasing of serum amyloid A (SAA) and C reactive protein (CRP) levels have been demonstrated in spirochetal infections." (PMID 30564101, 2018).
splenic hemangiosarcoma (1 paper, 2022). "One dog with splenic hemangiosarcoma died (CRP 16.6 μg/mL) and among 6 euthanized dogs CRP ranged from 25 μg/mL to 202.5 μg/mL." (PMID 36290272, 2022).
squamous cell tumors (1 paper, 2010). "It has been demonstrated that the increase of IL-8 and IL-6 and the increase of proteins such as C-reactive protein play an important role in the pathogenesis of H&N squamous cell tumors." (PMID 20184737, 2010).
strongyloidiasis (1 paper, 2023). An infection that is caused by nematodes of the genus Strongyloides, most commonly Strongyloides stercoralis, which is a soil-transmitted helminth, and which is characterized by a variety of gastrointestinal, dermatologic, and, occasionally, pulmonary manifestations. "In COVID patients co-infected with strongyloidiasis the most common manifestations were fever, low partial pressure of oxygen (pO2), patchy airspace opacities, leukocytosis, and elevated eosinophils, CRP, ferritin, and D-dimer." (PMID 37091061, 2023).
Subdural Effusion (1 paper, 2025). Leakage and accumulation of CEREBROSPINAL FLUID in the subdural space which may be associated with an infectious process; CRANIOCEREBRAL TRAUMA; BRAIN NEOPLASMS; INTRACRANIAL HYPOTENSION; and other conditions. "Our study found that patients aged [29 days, 1 year old), seizure, Escherichia coli in blood bacterial culture, and blood CRP >50 mg/L were independent risk factors of subdural effusion." (PMID 39974751, 2025). "On univariate analysis, the risk factors associated with subdural effusion were as follows: patients aged [29 days, 1 year old), seizure, Escherichia coli in blood bacterial culture, Escherichia coli in CSF bacterial culture, and blood CRP >50 mg/L." (PMID 39974751, 2025). "High CRP and Escherichia coli in blood bacterial culture were risk factors for subdural effusion that may be associated with blood–brain barrier function impairment caused by interleukin 6 or nitric oxide." (PMID 39974751, 2025).
Subglottic stenosis (1 paper, 2021). "Older age, male gender, smoking, elevated C-reactive protein level, subglottic stenosis, stent or T-tube implantation, previous interventional treatment, and multiple procedures per year were potentially associated with unsuccessful long-term outcomes in the univariate analysis." (PMID 33648488, 2021).
Superior Vena Cava Syndrome (1 paper, 2025). A condition that occurs when the obstruction of the thin-walled SUPERIOR VENA CAVA interrupts blood flow from the head, upper extremities, and thorax to the RIGHT ATRIUM. "Physical examination was reassuring, with no superior vena cava syndrome or respiratory distress, and all laboratory findings (CBC, CRP, LDH, tumor markers) were normal." (PMID 40861747, 2025).
supraventricular tachyarrhythmias (1 paper, 2023). "Another research team evaluated the C-reactive protein (CRP) levels and the incidence of anti-β1 antibodies in patients suffering from supraventricular tachyarrhythmias." (PMID 36768174, 2023).
Syncope (1 paper, 2011). A transient loss of consciousness (i.e., characterized by a rapid onset, a short duration, and a spontaneous and complete recovery) due to cerebral hypoperfusion. "We found that a single plasma value of CRP concentration is robustly associated with either syncope or SCA in BrS." (PMID 22203916, 2011).
T-cell neoplasms (1 paper, 2021). "The univariate Cox regression analysis showed that 6 parameters were significantly associated with OS including the Rad-score, T-cell neoplasms, white blood cell, hemoglobin, platelet count, and CRP (p < 0.05)." (PMID 35004761, 2021).
Tdp (1 paper, 2024). "There is also a possible correlation between QT-interval prolongation leading to another malignant arrhythmia, Torsades de pointes (Tdp), and increased CRP concentration." (PMID 38507154, 2024).
thymic carcinoma (1 paper, 2021). Thymic carcinoma (TC) is a type of thymic epithelial neoplasm characterized by a high malignant potential. "Indeed, in the current study we show that CRP is not prognostic in the thymic carcinoma and neuroendocrine subcohort." (PMID 34257595, 2021).
thyroid storm (1 paper, 2024). "Inflammatory markers, such as CRP and IL-6, have become a focal point, with elevated levels associated with the underlying inflammatory processes in the thyroid storm." (PMID 38552097, 2024). "Inflammatory Markers, such as C-reactive protein (CRP) and interleukin-6 (IL-6), have emerged in recent research as potential contributors to the diagnostic landscape, as their elevation can be indicative of thyroid storm." (PMID 38552097, 2024). "Recent research exploring the utility of inflammatory markers like CRP and IL-6 in diagnosing thyroid storm sparks debate." (PMID 38552097, 2024).
Tics (1 paper, 2024). Repeated, individually recognizable, intermittent movements or movement fragments that are almost always briefly suppressible and are usually associated with awareness of an urge to perform the movement. "Children with ocular tics had significantly higher titers of anti-DNase B antibodies (p = 0.04) and CRP (p = 0.016) than those with extraocular tics." (PMID 38785738, 2024). "The median CRP was 0.35 (range 0.26–0.4) mg/dL in PANDAS children with oculomotor tics and 0.14 (range 0.11–0.25) mg/dL in PANDAS children with extraocular tics, again not a significant difference (p = 0.49)." (PMID 38785738, 2024). "The median CRP was 0.35 (range 0.26–0.4) mg/dL in children with oculomotor tics and 0.14 (range 0.11–0.25) mg/dL in children with extraocular tics, again a statistically significant difference (p = 0.04)." (PMID 38785738, 2024).
Torticollis (1 paper, 2021). Involuntary contractions of the neck musculature resulting in an abnormal posture of or abnormal movements of the head. "Patients may show elevated C-reactive protein (CRP) levels and leucocyte counts in the first days of torticollis, followed by subsequent normalization of these parameters." (PMID 33922701, 2021).
toxic epidermal necrolysis (1 paper, 2025). Toxic epidermal necrolysis (TEN) is an acute and severe skin disease with clinical and histological features characterized by the destruction and detachment of the skin epithelium and mucous membranes. "Then, The MDA accumulation correlated positively with the disease severity of the severity-of-illness score for toxic epidermal necrolysis (SCORTEN), body surface area (BSA) and C-reactive protein (CRP) in patients with SJS/TEN (P < 0.05)." (PMID 39897035, 2025).
triple-negative breast carcinoma (1 paper, 2023). An invasive breast carcinoma which is negative for expression of estrogen receptor (ER), progesterone receptor (PR), and human epidermal growth factor receptor 2 (HER2). "The in vitro model showed that CRP activates the integrin α2 signaling pathways, demonstrating a role for CRP in the growth, acquisition of adhesive, and invasive phenotypes in breast and triple-negative breast cancer cells." (PMID 38000092, 2023).
tubal factor infertility (1 paper, 2019). Infertility caused by fallopian tube damage, preventing fertilisation or implantation. "Does C-reactive protein (CRP), as a marker of persisting low-grade inflammation, identify Chlamydia trachomatis IgG antibody test (CAT)-positive women who are at the highest risk for tubal factor infertility (TFI)?" (PMID 31858023, 2019).
undifferentiated carcinoma (1 paper, 2015). A usually aggressive malignant epithelial neoplasm composed of atypical cells which do not display evidence of glandular, squamous, or transitional cell differentiation. "Additionally, elevation of WBC count and CRP level can help the diagnosis of undifferentiated carcinoma." (PMID 25526684, 2015).
ureaplasma infection (1 paper, 2014). "Using the cut-off values derived from the ROC curves, elevated levels of CRP (≥7.46 mg/L) and NLR (≥6.48) were significantly associated with PIR, even after controlling for gestational age at hospitalization and delivery, monocytes, and ureaplasma infection." (PMID 25291377, 2014).
ureteritis (1 paper, 2023). An acute or chronic inflammatory process affecting the ureter. "The statistically significant differences in PCT and CRP levels among different infection sites, particularly within the subgroup of ureteritis, underscored the potential of these biomarkers in indicating the severity of infection." (PMID 37821527, 2023). "Notably, PCT and CRP exhibited enhanced utility in identifying ureteritis." (PMID 37821527, 2023). "The subgroup with ureteritis in the upper UTI category exhibited the highest PCT and CRP levels." (PMID 37821527, 2023).
vaginal infection (1 paper, 2025). "As expected, the average CRP value was also statistically significantly 8 times higher in pregnant women with vaginal infections." (PMID 40243431, 2025). "The difference in CRP values between the two groups was statistically significant, with higher levels observed in the vaginal infection group." (PMID 40243431, 2025).
vascular hypertrophy (1 paper, 2019). "Its administration produced a decrease in CRP and IL-6 levels and there was a positive correlation between CRP serum levels and the cross-sectional area, which is indicative of vascular hypertrophy." (PMID 31284520, 2019).
vascular occlusion (1 paper, 2020). "Several studies have shown a significant correlation between the vascular occlusion grade and baseline hs-CRP levels." (PMID 32466218, 2020).
vascular parkinsonism (1 paper, 2011). A Parkinsonism that is characterized by postural instability, a broad-based gait with the absence of tremors of vascular origin. "The association and clinical relevance of a combined assessment of Hcy and CRP levels in patients with PD and vascular parkinsonism (VP) are unknown." (PMID 21556377, 2011).
venous insufficiency (1 paper, 2018). Impaired venous blood flow or venous return (venous stasis), usually caused by inadequate venous valves. "Elevated levels of D-dimer, interleukin-6 (IL-6), interleukin-8 (IL-8), and C-reactive protein (CRP) levels were found within varicose vein blood in patients with venous insufficiency, compared with upper extremity blood samples." (PMID 29641492, 2018).
ventricular ectopy (1 paper, 2016). A type of cardiac arrhythmia with premature ventricular contractions or beats caused by signals originating from ectopic sites. "Increased level of NT-proBNP was independently associated with ventricular ectopy, whereas no independent association was observed between hs-TnI and hs-CRP levels and ventricular ectopy in this community-based sample." (PMID 27875987, 2016).
vestibular disorder (1 paper, 2022). Pathological processes of the vestibular labyrinth which contains part of the balancing apparatus. "The results indicate that frailty index may be still associated with an increased risk of vestibular disorders after adjustment for BMI, CRP, IBD and smoking." (PMID 36090295, 2022).
vestibular neuronitis (1 paper, 2019). Idiopathic inflammation of the vestibular nerve, characterized clinically by the acute or subacute onset of vertigo; nausea; and imbalance. "Vestibular neuronitis is typically linked to an acute inflammatory state, accompanied by elevated blood CRP." (PMID 31878146, 2019). "However, in our patient, vestibular neuronitis was accompanied by a very moderate and transient increase in blood CRP at the time of the AE occurrence." (PMID 31878146, 2019).
viral exanthem (1 paper, 2022). "A 2017 study comparing patients with viral exanthem and MDE found that the MDE group had a higher median absolute eosinophil count and serum C-reactive protein." (PMID 35466243, 2022).
volvulus (1 paper, 2022). "In multivariate analyses from other studies, elevated leukocyte count and CRP levels were independent risk factors for intestinal gangrene caused by volvulus." (PMID 35795333, 2022).
Von Willebrand disease (1 paper, 2019). von Willebrand disease (VWD) is a hereditary bleeding disorder caused by a genetic anomaly leading to quantitative, structural or functional abnormalities of the Willebrand factor (von Willebrand factor; VWF). "Two children of our non-febrile control group were excluded due to an elevated CRP (CRP 25 mg/l) with the suspicion of an underlying infection in one child, and the diagnosis of a mild inherited von Willebrand disease in another child." (PMID 30605489, 2019).
vulvar cancer (1 paper, 2025). "In gynecologic malignancies such as vulvar cancer, PCT and C-reactive protein (CRP) may assist in gauging the inflammatory response and in excluding concomitant infection; however, their sensitivity and specificity for direct tumor detection are low." (PMID 41464189, 2025).
Whipple disease (1 paper, 2020). A systemic infection caused by the Gram-positive bacterium Tropheryma whipplei. "Although the laboratory data showed a markedly increased level of CRP, which would also be typical for Whipple’s disease, the clinical features of the patient did not suggest this rare disorder." (PMID 32468113, 2020).
xanthomatosis (1 paper, 2014). A condition marked by the development of widespread xanthomas, yellow tumor-like structures filled with lipid deposits. "Interestingly, we observed that both forms of normolipidaemic xanthomatosis were associated with a common inflammatory pattern characterized by increased CRP and plasma levels of classical pro-inflammatory cytokines (IL-6 and TNFα)." (PMID 24428816, 2014).
ZIKV infection (1 paper, 2025). "In order to assess the overall level of peripheral inflammation within the first week of ZIKV infection, we characterized plasma levels of C-reactive protein (CRP), an acute-phase protein that has been used as an indicator of inflammatory responses." (PMID 40827913, 2025).